COQ8B (coenzyme Q8B)
Description:
Atypical kinase involved in the biosynthesis of coenzyme Q, also named ubiquinone, an essential lipid-soluble electron transporter for aerobic cellular respiration. Its substrate specificity is still unclear: may act as a protein kinase that mediates phosphorylation of COQ3. According to other reports, acts as a small molecule kinase, possibly a lipid kinase that phosphorylates a prenyl lipid in the ubiquinone biosynthesis pathway, as suggested by its ability to bind coenzyme Q lipid intermediates (By similarity). However, the small molecule kinase activity was not confirmed by another publication. Required for podocyte migration.
Synonyms: ADCK4; FLJ12229; COQ8; NPHS9
Tractability: Small molecule: a high-quality ligand is known; it belongs to a druggable protein family. Antibody: UniProt places it where antibodies can reach, with high confidence; UniProt predicts a signal peptide or a membrane-spanning region; its Gene Ontology location is reachable by antibodies, with medium confidence. PROTAC: it is named in the literature on targeted protein degradation; ubiquitination databases record sites on it; a small molecule that binds it is known.
Target class: Kinase; Atypical protein kinase group; Enzyme; Atypical protein kinase ABC1-A subfamily; Protein Kinase; Atypical protein kinase ABC1 family
Gene: Protein-coding gene on chromosome 19 (40,691,514 to 40,725,784, reverse strand). Ensembl gene ENSG00000123815.
Subcellular location: Mitochondrion membrane; Cytoplasm, cytosol; Cell membrane
Subcellular location (Human Protein Atlas): Mitochondria
Pathways (Reactome):
Metabolism: Ubiquinol biosynthesis
Gene Ontology:
Molecular function: protein kinase activity; ATP hydrolysis activity; lipid binding
Biological process: cerebellar Purkinje cell layer morphogenesis; protein phosphorylation; ubiquinone biosynthetic process
Cellular component: mitochondrial membrane; mitochondrion; plasma membrane; cytosol
Genetic constraint (gnomAD): Loss-of-function variants: 42 observed, 58.83 expected, observed/expected ratio (o/e) 0.71, 90% interval 0.56 to 0.92. The upper end of that interval is the gene's LOEUF score, 0.92, which puts it in group 3 of 6, group 1 being the genes least tolerant of losing a copy. Missense variants: 626 observed, 707.62 expected, observed/expected ratio (o/e) 0.88, 90% interval 0.83 to 0.94. Synonymous variants: 245 observed, 282.72 expected, observed/expected ratio (o/e) 0.87, 90% interval 0.78 to 0.96.
Gene-disease validity (ClinGen):
ClinGen rates the evidence that COQ8B causes each of these diseases.
mitochondrial disease (autosomal recessive): Definitive.
Homologues: Orthologues: chimpanzee COQ8B (99% identical), macaque COQ8B (96% identical), pig COQ8B (88% identical), rabbit COQ8B (87% identical), mouse Coq8b (85% identical), guinea pig COQ8B (85% identical), rat Coq8b (82% identical), tropical clawed frog coq8b (60% identical), zebrafish coq8b (59% identical), Drosophila melanogaster Coq8 (46% identical), Caenorhabditis elegans coq-8 (44% identical). Paralogues in human: COQ8A (54% identical), ADCK5 (20% identical), ADCK1 (19% identical), ADCK2 (17% identical).
Diseases named in the same sentence as COQ8B in open-access papers:
COQ8B is named in the same sentence as 45 diseases in open-access papers, as found by Europe PMC text mining. Sharing a sentence is not in itself a finding about the gene and the disease. The quoted sentences say what the papers report.
Nephropathy (21 papers, 2017 to 2025). A nonspecific term referring to disease or damage of the kidneys. "We identified three adult-onset COQ8B nephropathy patients with COQ8B c.737G > A variant from unrelated Chinese families." (PMID 40356518, 2025). "COQ8B nephropathy, an autosomal recessive disease caused by mutation in COQ8B gene, is one of the most common single-gene causative glomerulopathy of pediatric SRNS and is one of the few genetic FSGS form with a targeted therapy available." (PMID 40356518, 2025). "There are limited reports describing the pathogenic effects of COQ8B variants on CoQ biosynthesis and other related mitochondrial functions, especially in children with kidney disease." (PMID 39877334, 2024). "Insights from structural modeling suggest that pathogenic variants in COQ8B alter allosteric regulation or protein folding and stability in renal disease." (PMID 39877334, 2024). "COQ8B variants mainly cause a phenotype with kidney damage and nephrotic syndrome (nephrotic syndrome type 9; NPHS9; OMIM #615573)." (PMID 36978966, 2023). "COQ8B (ADCK4)-associated nephropathy is related to mitochondrial dysfunction, which is caused by COQ8B gene variants." (PMID 36843884, 2022). "COQ8B has an important but incompletely defined role in the biosynthesis of CoQ, and recessive mutations are associated with a nephropathy (NPHS9 [MIM: 615573]) that typically manifests in adolescence." (PMID 34917985, 2022). "Screens for COQ8B mutations in patients with renal disorders, including nephrotic syndrome and chronic renal failure, were described in three studies, which in total reported the identification of 63 COQ8B patients." (PMID 35985679, 2022). "Genetic testing revealed COQ8B mutation (c.532C > T, p.R178W); therefore, we diagnosed COQ8B nephropathy." (PMID 32859164, 2020). "Mutations in COQ8B/ADCK4 account for the highest number of patients with kidney disease secondary to CoQ10 deficiency." (PMID 33305107, 2020). "Notably, the onset of renal disease caused by pathogenic variants of COQ8B can occur in adolescence or after the age of 30." (PMID 39625678, 2025). "Thus, mutations in the COQ8B/ADCK4 gene account for the highest number of primary CoQ10 deficiency patients with kidney disease." (PMID 38722242, 2024). "Our COQ8B nephropathy cohort presented the distinct mutation spectrum of COQ8B in Chinese patients." (PMID 32543055, 2020). "Previous research reported that CoQ10 nephropathy due to mutations in genes such as PDSS2, COQ2, COQ6, and COQ8B is identified in approximately 1–2.7% of SRNS cases." (PMID 39805995, 2025). "According to some non-Chinese case reports, COQ8B gene mutation causes adolescence-onset nephropathy." (PMID 36034551, 2022). "The five genes COL4A5, COQ8B, NPHP1, PAX2, and WT1 accounted for 66.9% of the monogenetic kidney disease diagnoses." (PMID 39363361, 2024).
nephrotic syndrome (17 papers, 2017 to 2024). A collection of symptoms that include severe edema, proteinuria, and hypoalbuminemia; it is indicative of renal dysfunction. "The cause of CKD is these siblings is unclear but the twin brothers are heterozygous for a mutation in a recently described nephrotic syndrome-associated gene, COQ8B (NM_024876.3, c.532C>T, p.Arg178Trp)." (PMID 39435356, 2024). "The COQ8B gene (also known as ADCK4) similarly encodes an atypical protein kinase, variants in which result in steroid-resistant nephrotic syndrome with variable neurological involvement (presenting mainly in childhood or adolescence)." (PMID 37627647, 2023). "CoQ10 deficiency is the cause of several human diseases, and mutations in the COQ8B gene result mainly in the disruption of kidney function, causing a steroid-resistant nephrotic syndrome." (PMID 36769128, 2023). "Several other studies have also reported different genetic substitutions at locus chr19:41209497 of the COQ8B gene causing nephrotic syndrome." (PMID 34172776, 2021). "For example, our knowledge of COQ8B variants largely comes from two studies in which large numbers of patients with nephrotic syndrome were subjected to sequencing of either whole exomes or multi-gene panels designed for nephrotic syndrome." (PMID 29255295, 2017). "Thus, COQ8B gene mutations can cause primary CoQ10 deficiency and glomerular podocyte injury resulting in COQ8B glomerular nephropathy (COQ8B-GN) or nephrotic syndrome type 9 (NPHS9), which commonly manifests as a steroid-resistant nephrotic syndrome (SRNS)." (PMID 36034551, 2022). "Several pathogenic mutations in the COQ8B gene are known to cause nephrotic syndrome." (PMID 34172776, 2021). "COQ8B-GN had insidious onset with various clinical manifestations, including asymptomatic proteinuria, nephrotic syndrome (NS), or SRNS." (PMID 36034551, 2022). "The clinical manifestations of nephrotic syndrome, the effacement of the foot process, and a damage to the slit diagram in podocytes were observed in the COQ8B knockout animal model." (PMID 36843884, 2022). "Coenzyme Q8B (OMIM * 615567) glomerular nephropathy (COQ8B-GN) or nephrotic syndrome type 9 (NPHS9, OMIM # 615573) is an autosomal recessive type of CKD, inherited through allelic homogeneous variant or compound heterozygous variants." (PMID 34172776, 2021). "Mutations in COQ8A and COQ8B (previously known as ADCK3 and ADCK4) have been shown to induce a decrease of CoQ in the cerebellum and kidney causing cerebellar ataxia and nephrotic syndrome, respectively." (PMID 31480808, 2019).
glomerulopathy (8 papers, 2017 to 2024). "A recent multicenter study reported that the founder mutations of COQ8B led to regional variations in the incidence of CoQ10 deficiency-associated glomerulopathy, and confirmed the geographical clustering of the recurrent variants of COQ8B in China." (PMID 39363361, 2024). "Here, we report the clinical features and therapeutic responses of 4 pediatric patients with glomerular disease due to COQ8B variants." (PMID 39877334, 2024). "For the 22 patients diagnosed with Coenzyme Q10 (CoQ10) deficiency-associated glomerulopathy caused by the pathogenic variants of COQ8B, oral supplementation with CoQ10 should be continued following transplantation." (PMID 39363361, 2024). "Mutations in PDSS2, COQ2, COQ6, and COQ8B/ADCK4 are frequently associated with glomerular disease, mainly steroid-resistant nephrotic syndrome (SRNS)." (PMID 38722242, 2024). "COQ8B gene variant-related glomerulopathy is a recently recognized glomerular disease associated with coenzyme Q deficiency that most commonly manifests in early childhood as SRNS with FSGS histopathology that can progress to kidney failure." (PMID 39877334, 2024). "Mutations in genes related to coenzyme Q10, another mitochondrially associated antioxidant, including PDSS1, PDSS2, COQ2, COQ6, and COQ8B/ADCK4, are associated with the development of glomerular disease." (PMID 34874915, 2022). "The histopathology of COQ8B-related glomerulopathy lacks pathognomonic morphological features, and the specific mechanism of its predisposition to FSGS is unknown." (PMID 39877334, 2024). "As COQ8B mutations have been implicated in steroid-resistant nephrotic syndrome (SRNS) in patients, a podocyte-specific Coq8b KO model (Nphs2-Cre;Coq8bloxP/loxP) was generated and the mice were shown to present with glomerulopathy and renal dysfunction that started at ∼4 mo." (PMID 38722242, 2024). "COQ8B-associated glomerulopathy often presents as SRNS with no obvious extrarenal manifestations." (PMID 39877334, 2024).
chronic kidney disease (5 papers, 2017 to 2022). Impairment of the renal function secondary to chronic kidney damage persisting for three or more months. "Mutation in the COQ8B gene can cause COQ8B glomerular nephropathy (COQ8B-GN), which is rare and associated with steroid-resistant nephrotic syndrome (SRNS) as well as rapid progression to end-stage renal disease (ESRD)." (PMID 36034551, 2022). "We identified 20 (5.8%) patients with biallelic mutations of COQ8B screening for patients with SRNS, non‐nephrotic proteinuria, or chronic kidney disease (CKD) of unknown origin." (PMID 32543055, 2020).
kidney failure (5 papers, 2020 to 2024). An acute or chronic condition that is characterized by the inability of the kidneys to adequately filter the blood. "Reports suggest that COQ8B-related glomerulopathy is a progressive disease and an important consideration in the differential diagnosis for adolescent kidney failure patients." (PMID 39877334, 2024).
steroid-resistant nephrotic syndrome (5 papers, 2018 to 2024). Nephrotic syndrome, occurring in the pediatric population, in which proteinuria does not normalize with administration of steroids; this condition is unresponsive to a minimum of four weeks administration of oral corticosteroids. "Among the so far studied genes, 4: PDSS2/COQ1, COQ2, COQ6, and ADCK4/COQ8B are associated with steroid-resistant nephrotic syndrome (SRNS)—they are mutated in about 1% of cases." (PMID 30232548, 2018).
coenzyme Q10 deficiency (2 papers, 2020 to 2024). A genetically heterogeneous condition, typically inherited in an autosomal recessive fashion, characterized by coenzyme Q10 deficiency. "Coenzyme Q10 deficiency can result from pathogenic variants in the COQ2, COQ4, COQ6, COQ8A, or COQ8B gene." (PMID 38570878, 2024).
retinitis pigmentosa (1 paper, 2024). Retinitis pigmentosa (RP) is an inherited retinal dystrophy leading to progressive loss of the photoreceptors and retinal pigment epithelium and resulting in blindness usually after several decades. "We identified DNA changes in a gene, COQ8B, that can lead to retinitis pigmentosa, a hereditary form of blindness." (PMID 39226897, 2024).
mitochondrial disease (1 paper, 2024). "In rare cases, specific therapies may exist for mitochondrial diseases caused by single-gene pathogenic variants such as COQ2, COQ6, or COQ8b." (PMID 38877226, 2024).
COQ8B also shares sentences with these, for which no sentence is quoted: focal segmental glomerulosclerosis (4 papers); cancer (3); nephrotic syndrome type 9 (3); Ataxia (2); Cerebellar atrophy (2); Crohn disease (2); end-stage renal disease (2); hypertrophic cardiomyopathy (2); lactic acidosis (2); Progressive encephalopathy (2); renal failure (2); Adult onset (1); Alport syndrome (1); autosomal dominant polycystic kidney disease (1); cerebellar ataxia (1); Charcot-Marie-Tooth disease (1); ciliopathies (1); colorectal cancer (1); congenital nephrotic syndrome (1); cystic kidney disease (1); Diarrhea (1); encephalomyopathy (1); Encephalopathy (1); Fundus dystrophy (1); Immunodeficiency (1); Leigh syndrome (1); MELAS (1); Mitochondrial myopathy (1); nemaline myopathy (1); nephritis (1).
A further 6 diseases each share a sentence with COQ8B in 1 paper.